GNAI2 (G protein subunit alpha i2)
Description:
Guanine nucleotide-binding proteins (G proteins) function as transducers downstream of G protein-coupled receptors (GPCRs) in numerous signaling cascades. The alpha chain contains the guanine nucleotide binding site and alternates between an active, GTP-bound state and an inactive, GDP-bound state. Signaling by an activated GPCR promotes GDP release and GTP binding. Examples of interacting GPCRs include the adenosine A1 receptor/ADORA1, CNR1, and FPR2. The alpha subunit has a low GTPase activity that converts bound GTP to GDP, thereby terminating the signal. Both GDP release and GTP hydrolysis are modulated by numerous regulatory proteins. Signaling is mediated via effector proteins, such as adenylate cyclase: inhibits adenylate cyclase activity of ADCY1, ADCY5 and ADCY6, leading to decreased intracellular cAMP levels. Plays an important role in the activation of the transcription factor NFAT in endothelial cells to promote angiogenesis. The G(i) proteins are involved in hormonal regulation of adenylate cyclase: they inhibit the cyclase in response to beta-adrenergic stimuli. Plays an essential role for neutrophil recruitment in the context of acute inflammation suggesting a linked function of both GNAI2 in neutrophils and endothelial cells for polymorphonuclear neutrophils transmigration (By similarity). [Isoform sGi2]: Regulates the cell surface density of dopamine receptors DRD2 by sequestrating them as an intracellular pool.
Synonyms: GNAI2B; GIP; HG1C; H_LUCA15.1; H_LUCA16.1
Tractability: Small molecule: a structure with a bound ligand is known. Antibody: UniProt places it where antibodies can reach, with high confidence; its Gene Ontology location is reachable by antibodies, with high confidence; the Human Protein Atlas places it where antibodies can reach. PROTAC: ubiquitination databases record sites on it; its protein half-life has been measured; a small molecule that binds it is known.
Target class: Other membrane protein
Gene: Protein-coding gene on chromosome 3 (50,226,292 to 50,259,362, forward strand). Ensembl gene ENSG00000114353.
Subcellular location: Cytoplasm; Cytoplasm, cytoskeleton, microtubule organizing center, centrosome; Cell membrane; Membrane
Subcellular location (Human Protein Atlas): Cytosol; Basal body; Nucleoplasm; Plasma membrane
Pathways (Reactome):
Signal Transduction: Extra-nuclear estrogen signaling; G alpha (i) signalling events; G alpha (s) signalling events; G alpha (z) signalling events; GPER1 signaling
Metabolism: Adrenaline,noradrenaline inhibits insulin secretion; Regulation of insulin secretion
Disease: ADORA2B mediated anti-inflammatory cytokines production
Hemostasis: ADP signalling through P2Y purinoceptor 12
Neuronal System: Adenylate cyclase inhibitory pathway
Gene Ontology:
Molecular function: GTPase activity; protein binding; G protein-coupled receptor binding; G-protein beta/gamma-subunit complex binding; GTP binding; guanyl nucleotide binding
Biological process: angiogenesis; cell division; positive regulation of cell population proliferation; adenylate cyclase-inhibiting G protein-coupled receptor signaling pathway; G protein-coupled adenosine receptor signaling pathway; G protein-coupled receptor signaling pathway; gamma-aminobutyric acid signaling pathway; negative regulation of adenylate cyclase activity; response to nutrient; signal transduction; adenylate cyclase-activating G protein-coupled receptor signaling pathway; adenylate cyclase-modulating G protein-coupled receptor signaling pathway; modulation of chemical synaptic transmission; negative regulation of adenylate cyclase-activating adrenergic receptor signaling pathway; negative regulation of apoptotic signaling pathway; negative regulation of calcium ion-dependent exocytosis; negative regulation of synaptic transmission; positive regulation of cell migration; positive regulation of ERK1 and ERK2 cascade; positive regulation of neural precursor cell proliferation; positive regulation of superoxide anion generation; positive regulation of urine volume; positive regulation of vascular associated smooth muscle cell proliferation; regulation of calcium ion transport
Cellular component: centrosome; cytoplasm; cytoplasmic side of plasma membrane; cytosol; extracellular exosome; extracellular vesicle; membrane; midbody; plasma membrane; cell body; dendrite; hippocampal mossy fiber to CA3 synapse; neuronal dense core vesicle
Genetic constraint (gnomAD): Loss-of-function variants: 3 observed, 34.08 expected, observed/expected ratio (o/e) 0.088, 90% interval 0.039 to 0.23. The upper end of that interval is the gene's LOEUF score, 0.23, which puts it in group 1 of 6, group 1 being the genes least tolerant of losing a copy. Missense variants: 214 observed, 450.54 expected, observed/expected ratio (o/e) 0.47, 90% interval 0.42 to 0.53. Synonymous variants: 187 observed, 186.58 expected, observed/expected ratio (o/e) 1, 90% interval 0.89 to 1.13.
Homologues: Orthologues: chimpanzee GNAI2 (100% identical), macaque GNAI2 (100% identical), pig GNAI2 (99% identical), dog GNAI2 (99% identical), guinea pig GNAI2 (99% identical), rat Gnai2 (99% identical), mouse Gnai2 (98% identical), rabbit GNAI2 (98% identical), tropical clawed frog gnai2 (94% identical), zebrafish gnai2b (92% identical), zebrafish gnai2a (87% identical), Caenorhabditis elegans gpa-3 (50% identical), and 10 more. Paralogues in human: GNAI1 (88% identical), GNAI3 (86% identical), GNAT2 (70% identical), GNAO1 (69% identical), GNAT3 (68% identical), GNAT1 (66% identical), GNAZ (66% identical), GNAQ (51% identical), GNA11 (51% identical), GNA14 (51% identical), GNAL (45% identical), GNA15 (44% identical), and 3 more.
Diseases named in the same sentence as GNAI2 in open-access papers:
GNAI2 is named in the same sentence as 70 diseases in open-access papers, as found by Europe PMC text mining. Sharing a sentence is not in itself a finding about the gene and the disease. The quoted sentences say what the papers report.
ovarian carcinoma (10 papers, 2012 to 2024). A malignant neoplasm originating from the surface ovarian epithelium. "In this context, it is of interest to note that the α-subunit of G protein i2, which is encoded by the gene GNAi2 and often referred to as gip2 proto-oncogene, shows a biased increased expression in the late stages of ovarian cancer." (PMID 34439877, 2021). "Increased expression of GNAi2, which encodes the α-subunit of G-protein i2, has been correlated with the late-stage progression of ovarian cancer." (PMID 34439877, 2021). "The mechanisms associated with the regulation of GNAI2 expression in cancer cells and specifically in ovarian cancer is poorly understood." (PMID 27811362, 2016). "Suppression of GNAI2 has been detected in ovarian cancer and somatic GNAI2 mutations have been identified in diffuse large B-cell lymphoma." (PMID 26588071, 2015). "By being situated upstream of regulatory mechanisms that control both proliferation and migration, GNAI2 could prove to be a useful diagnostic indicator or potential therapeutic target in ovarian cancer." (PMID 24423449, 2014). "Literature search reveals that GNAI1 is involved in prostate cancer growth and GNAI2 is essential in prostate cancer cell migration and invasion and is also a crucial regulator in another hormone-dependent cancer, ovarian cancer." (PMID 38983753, 2024). "The role of gip2 in ovarian cancer pathobiology becomes all the more important considering the fact that GNAi2 is activated by lysophosphatidic acid (LPA), an endogenous growth factor in ovarian cancer." (PMID 34439877, 2021). "The identification of these genes as the critical nodes in GNAi2/gip2 orchestrated onco-transcriptome establishes their role in ovarian cancer pathophysiology." (PMID 34439877, 2021). "Modifications of the GNAI2 protein have been detected in other malignancies as well, such as ovarian cancer, wherein an abundance of GNAI2 leads to an uncontrolled proliferation of cells." (PMID 34946938, 2021). "Our previous studies have shown that LPA-LPAR activation or mutational activation of GNAi2/gip2 stimulates proliferation, EMT, invasive migration, and metabolic reprogramming of ovarian cancer cells." (PMID 34439877, 2021). "We described GNAI2 as a direct target of miR-222-3p that controls cell proliferation in ovarian cancer cells." (PMID 27811362, 2016). "We describe the characterization of a novel regulatory axis in ovarian cancer cells, miR-222-3p/GNAI2/AKT and its potential application as a therapeutic target for EOC patients." (PMID 27811362, 2016). "We began by investigating the human Origene ovarian cancer array (OCA) using direct sequencing within the coding region of GNAI2 transcripts." (PMID 24423449, 2014). "Furthermore, GNAI2 has been found to facilitate the proliferation of ovarian cancer cells (EOCs) through involvement in the miR-222-3p/GNAI2/AKT pathway." (PMID 39063192, 2024). "In this regard, the observation that GNAi2/gip2 shows increased expression in advanced ovarian cancers is quite significant as it suggests the possibility that gip2 could play a critical, if not unique, role in advanced ovarian cancers." (PMID 34439877, 2021). "Here we elucidate GNAI2 message alterations in ovarian cancer (OvCa)." (PMID 24423449, 2014). "GNAI2 was found to be underexpressed in the majority of the ovarian cancer patient population." (PMID 24423449, 2014). "Dataset GSE:29450 confirmed the trend of underexpression of GNAI2 in ovarian cancer cells." (PMID 24423449, 2014). "In ovarian cancer cells, GNAI2 mediated lysophosphatidic acid-induced migration." (PMID 23691483, 2012). "To identify the oncogenic program activated by gip2, we carried out micro-array-based transcriptomic and bioinformatic analyses using the ovarian cancer cell-line SKOV3, in which the expression of GNAi2/gip2 was silenced by specific shRNA." (PMID 34439877, 2021).
ovarian carcinoma (continued). "GNAi2, also referred to as the proto-oncogene gip2, transduces signals from lysophosphatidic acid (LPA)-activated LPA-receptors to oncogenic cellular responses in ovarian cancer cells." (PMID 34439877, 2021). "Considering the late-stage expression profile of GNAi2/gip2 in ovarian cancer, the hub and bottleneck nodes identified here, especially the metabolic signaling nodes such as UQCRFS1, should provide newer targets for the development of second-line targeted therapy for advanced ovarian cancers." (PMID 34439877, 2021). "Among the down-regulated candidates (data not shown), only GNAI2 has been previously reported to be an activator of AKT; therefore, we evaluated GNAI2 mRNA expressions in the six ovarian cancer cell lines by qRT-PCR." (PMID 27811362, 2016).
colitis (7 papers, 2013 to 2024). Inflammation of the colon. "For instance, GNAI2-deficient C57BL/6 mice are relatively resistant to colitis, whereas GNAI2-deficient 129 mice develop IBD earlier and with greater frequency and severity." (PMID 39273699, 2024). "GNAI3 is a potential tumor suppressor, which inhibits GNAI2-mediated myeloid-derived suppressor cells (MDSCs) proliferation and Colitis-Associated tumorigenesis by negatively regulating IL6 signaling pathway." (PMID 36042374, 2022). "However, the GNAI2-deficient mouse model paradoxically develops spontaneous colitis that resembles human IBD." (PMID 39273699, 2024). "Additional association with colitis susceptibility in Gnai2-/- mice suggests that this locus may govern key inflammatory pathways in disease development, irrespective of trigger." (PMID 23442222, 2013). "For example, GNAI1 and GNAI3 were found to reduce colitis-associated tumorigenesis in mice through blocking of IL6 signaling and down-regulation of the expression of GNAI2." (PMID 34992636, 2021). "In IBD, MAGI2, GNAI2, MIO9B, PTPN2, and CDH1 genes have been identified as tight junction assembly and barrier function regulators and were significantly associated with colitis." (PMID 33806347, 2021).
hepatocellular carcinoma (6 papers, 2012 to 2025). A malignant tumor that arises from hepatocytes. "MiRNA 30d-5p was shown to bind GNAI2 in a hepatocellular carcinoma (HCC) via luciferase reporter assay technology, where miRNA 30d-5p associated GAI2 knockdown increased HCC cell migration and invasion." (PMID 24432306, 2013). "Interestingly, in hepatocellular carcinoma, miR-30d significantly promoted HCC cell invasion and metastasis by targeting GNAI2." (PMID 27811362, 2016).
atherosclerosis (5 papers, 2020 to 2023). A disease characterized by the build-up of fatty material and calcium deposition in the arterial wall resulting in partial or complete occlusion of the arterial lumen. "The level of melatonin is decreased in serum of mice with diabetes-accelerated atherosclerosis, and exogenous supplement of melatonin reduces iNOS expression and S-nitrosylation of GNAI2, thus alleviating diabetes-accelerated atherosclerosis." (PMID 34294713, 2021). "Taken together, these results suggest that S-nitrosylation of GNAI2 is elevated in diabetes-accelerated atherosclerosis." (PMID 34294713, 2021). "In conclusion, we found S-nitrosylation of GNAI2 at Cys66-mediated diabetes-accelerated atherosclerosis." (PMID 34294713, 2021). "On this basis, present study uncovered that SNHG1 attenuated atherosclerosis via up-regulating GNAI2 and PCBP1." (PMID 32536864, 2020). "In addition, we showed that melatonin treatment restored endothelial function and protected against diabetes-accelerated atherosclerosis by preventing GNAI2 S-nitrosylation." (PMID 34294713, 2021). "G-protein alpha-i2, coded by GNAI2, is related to chemokine receptor signaling, including CXCR5 signaling, which is thought to induce Hippo/YAP-dependent DM-accelerated atherosclerosis." (PMID 36077273, 2022). "Here the authors show that the coupling efficiency of GNAI2 with CXCR5 is enhanced by S-nitrosylation of GNAI2, leading to Hippo-YAP dysfunction in endothelium, and plays a role in diabetes-accelerated atherosclerosis." (PMID 34294713, 2021).
breast carcinoma (4 papers, 2012 to 2025). "For instance, low GNAI2 expression correlates with trastuzumab resistance in HER2-positive breast cancer, while GNAI1 overexpression has been linked to poor survival and chemoresistance in advanced-stage ovarian tumors." (PMID 40819057, 2025). "Prior research has shown that GNAI2 is hypermethylated in breast cancer, supporting our findings." (PMID 40819057, 2025). "Although GNAI2 has been linked to resistance in trastuzumab-treated breast cancer, no previous studies have addressed the association between GNAI gene expression and chemoresistance in COAD, highlighting the novelty of this observation and its therapeutic relevance." (PMID 40819057, 2025). "Previous studies have shown that GNAI2 regulates EMT in pancreatic and breast cancer via ERK signaling, and GNAI1 impacts DNA damage repair via ATM/CHK2 pathway modulation in glioblastoma." (PMID 40819057, 2025).
colorectal cancer (4 papers, 2016 to 2025). A primary or metastatic malignant neoplasm that affects the colon or rectum. "Together, our identified mechanism, patient data, and the phenotype of Gnai2 knockout mice suggest a tumor suppressor function of Gαi2 in colorectal cancer." (PMID 35115535, 2022). "Inactivating GNAI2 alterations occur in about 6% of colorectal cancer patients, which is about the frequency of oncogenic β-catenin (5%) or conductin (7%) mutations but far below the loss of APC (77%), the major tumor suppressor of the Wnt pathway." (PMID 35115535, 2022). "In colorectal cancer, The Cancer Genome Atlas (TCGA) data sets COAD and READ showed loss of GNAI2 gene copies in about 5% of the cases, and decreased GNAI2 mRNA expression compared to healthy tissue." (PMID 35115535, 2022). "Future studies involving metabolic flux analysis, DNA damage assays, and drug treatment experiments are warranted to explore these hypotheses and further elucidate the mechanistic roles of GNAI1 and GNAI2 in colorectal cancer biology and therapy response." (PMID 40819057, 2025).
gastric cancer (4 papers, 2023 to 2024). A primary or metastatic malignant neoplasm involving the stomach. "Finally, we carried out qRT-PCR analysis of the expression levels of RGS2, GNAI2, ANXA5, MARCKS, CD36, NRP1, and PDE4A in gastric cancer cells." (PMID 38274323, 2024).
melanoma (4 papers, 2012 to 2023). A malignant, usually aggressive tumor composed of atypical, neoplastic melanocytes. "So far statistically significant mutation of GNAI2 in melanoma has not been reported." (PMID 25600636, 2015).
Anxiety (3 papers, 2020 to 2021). Intense feelings of nervousness, tension, or panic often arise in response to interpersonal stresses. "The results showed that Gfap, Rhog, Gnai2, Ppp1r1b, and Uqcrh were specifically dysregulated in the prefrontal cortex of the depression-susceptible group, while Tubb6, Urod, Cul1, Spred1, and Gpcpd1 were specifically dysregulated in the anxiety-susceptible group." (PMID 33627638, 2021). "In vivo studies have shown GNAI2 knockdown mice to exhibit a lack of social interaction, increased anxiety, and long-term depression." (PMID 33888815, 2021). "Additionally, in vivo studies conducted with GNAI2‐knockdown mice determined a lack of social interaction, recognition and increased anxiety in these mice." (PMID 32929144, 2020).
colon tumor (3 papers, 2021 to 2022). "In a mouse model, GNAI1 and GNAI 3 suppressed DSS-plus-azoxymethane-induced colon tumor development, whereas the expression of GNAI2 in CD11c+ cells and interleukin-6 (IL6) in CD4+/CD11b+ dendritic cells appeared to promote these effects." (PMID 35743732, 2022). "The expression of GNAI2 in CD11c+ cells and IL6 in CD4+/CD11b+ DCs appears to promote colon tumor development in mice." (PMID 33828969, 2021).
Hypertension (3 papers, 2015 to 2022). The presence of chronic increased pressure in the systemic arterial system. "Our translational human genomic studies have identified three G protein subunit alpha I2 (GNAI2) single nucleotide polymorphisms (SNPs) as potential biomarkers in individuals with salt sensitivity and essential hypertension." (PMID 35837296, 2022). "Additionally, studies in an Italian European cohort have suggested that a single C>G mutation in the GNAI2 promoter region reduces the binding of the specificity protein 1 (Sp1) transcription factor and is associated with hypertension." (PMID 35837296, 2022). "SNP rs4547694 has a Minor Allele Frequency (MAF) of 38.1%, suggesting that this GNAI2 SNP may be a prevalent marker that is associated with essential hypertension in at-risk individuals of European ancestry." (PMID 35837296, 2022). "SNPs in the GNAI2 gene are associated with increased hypertension risk in Caucasian Italians and in the Millennium Genome Project for Hypertension in Japan, providing the first evidence of the potential utility of GNAI2 SNPs as a biomarker of hypertension risk." (PMID 26347659, 2015). "Based on our prior animal studies that report a role for brain Gαi2 proteins in the salt sensitivity of BP and evidence that GNAI2 single nucleotide polymorphisms (SNPs) associate with hypertension risk, we investigated the hypothesis that GNAI2 SNPs associate with salt sensitivity of BP in humans." (PMID 29906209, 2018). "Our recent studies have identified two additional SNPs in the human GNAI2 gene, rs2298952 and rs4547694, which significantly correlate with essential hypertension in UK BioBank data set of individuals of European ancestry." (PMID 35837296, 2022).